CD8A (CD8 subunit alpha)
Diseases named in the same sentence as CD8A in open-access papers (continued):
Sharing a sentence is not in itself a finding about the gene and the disease.
brain tumors (93 papers, 2002 to 2026). "When combined with anti-PD-1 therapy, KCTD10 overexpression significantly inhibited metastatic lung and brain tumor colonization and led to the strongly improvement in CD8a+ T cell infiltration." (PMID 40873559, 2025). "Collectively, these observations suggest that the tumor vascular wall in the dKO mice was permeable to both fluorescent dyes (plasma) and blood cells, allowing the massive entry of CD8α+ T cells into the brain tumor milieu." (PMID 40408475, 2025).
colorectal tumors (93 papers, 2010 to 2025). "Looking at cancers individually, it is interesting that colorectal tumors, many of which had very high mutational loads, showed the strongest association between predicted immunogenic mutation counts and CD8A expression." (PMID 24782321, 2014).
Splenomegaly (91 papers, 2007 to 2026). Abnormal increased size of the spleen. "Confirming this predicted tolerogenic phenotype in our model, CD8α+ DC deficiency in B6.Batf3−/− mice significantly enhanced the severity of cGVHD, including splenomegaly and lymphocyte activation, thus confirming the predicted tolerogenic phenotype in our model." (PMID 29868014, 2018). "Regarding the absolute numbers and according to the splenomegaly, all groups of infected mice showed an increase in the absolute number of CD11c+ CD8α+ DCs as compared to non-infected mice." (PMID 34295832, 2021).
thymoma (90 papers, 2010 to 2026). A neoplasm arising from the epithelial cells of the thymus. "Patients with hyperplasia and thymoma differed in several proteins, including IL-18R1, TRAIL, CCL23, CX3CL1, CD8A, IL-8, TNF-β, and CCL11." (PMID 39165841, 2024). "Lentiviral vectors expressing M-1 or M-4 isoform were transduced into the JM thymoma cells (CD4+, CD8α+, CD8β−) to generate stable cell lines that differed only in the expression of each CD8β isoform." (PMID 23533620, 2013). "In thymomas, CD8A expression, which has been shown to quantify CD8 T-cells in tumor samples, is high across all TIS scores and weakly negatively correlated with TIS score, likely because the tumor occurs in the thymus, the site of lymphocyte (T and B cell) maturation." (PMID 29929551, 2018).
B-cell lymphoma (88 papers, 2011 to 2026). "A CD19 CAR T-cell product containing a longer CD8α-HD/TMD was found to be associated with lower cytokine production, inducing no severe CRS or ICANS in 25 patients with refractory B cell lymphoma." (PMID 34794490, 2021).
hepatitis B (88 papers, 2007 to 2025). "We investigated the diagnostic properties of quantitative values of the biomarkers CCL-20, CXCL-16, CD8a, and GDF-15 in predicting hepatitis B using ROC curve analysis." (PMID 41157623, 2025).
chronic hepatitis B (84 papers, 2008 to 2025). "CD8a was found to be an effective biomarker for distinguishing disease severity in patients with chronic hepatitis B, with quantitative values up to 11.33 indicating mild disease, values between 11.33 and 24.391 indicating moderate disease, and values of 24.391 and above indicating severe disease." (PMID 41157623, 2025). "Our study has revealed valuable information that GDF-15, CCL-20, CXCL-16, and CD8a biomarkers, which can be measured quantitatively by a simple and cost-effective ELISA method, can be a tool that can support molecular testing (PCR) in the clinical management of chronic hepatitis B patients." (PMID 41157623, 2025). "This study has shown that the biomarkers GDF-15 and CCL-20 may be potential diagnostic biomarkers in detecting the presence of chronic hepatitis B, and the biomarkers CXCL-16, CCL-20, GDF-15, and CD8a may be potential diagnostic biomarkers in determining the severity of the disease." (PMID 41157623, 2025). "Our study investigated four biomarkers, providing promising results that are more comprehensive and detailed for diagnosing and staging chronic hepatitis B. Each biomarker captures a different aspect of the disease: GDF-15 (stress/injury), CCL-20 (inflammation), and CXCL-16/CD8a (T cell dynamics)." (PMID 41157623, 2025).
mesothelioma (81 papers, 2013 to 2026). A usually malignant and aggressive neoplasm of the mesothelium which is often associated with exposure to asbestos. "However, examination of DC subsets showed that mesothelioma significantly decreased cross presenting CD8α+CD11b− cDC and T helper 2 (Th2) cell-activating CD11b+CD8α−CD4− cDC proportions in TDLNs compared to LNs from age-matched healthy mice." (PMID 30560130, 2018). "In summary, this study showed that mesothelioma tumors and their secreted factors promote DC lipid accumulation, reduce DC numbers, in particular cross-presenting CD8α+CD4- DCs, impair antigen processing and antigen presentation ability and skew DCs to produce tolerogenic cytokines." (PMID 25886502, 2015). "Furthermore, our in vivo mesothelioma studies showed that CD8α+CD4- DCs were reduced in dLN and spleen, implying that cross-presentation of antigens is impaired in lymphoid organs." (PMID 25886502, 2015). "In vivo studies using a murine mesothelioma model showed that the lipid content of tumor-infiltrating CD4+CD8α- DCs, CD4-CD8α- DCs DCs and plasmacytoid DCs increased with tumor progression." (PMID 25886502, 2015).
colon adenocarcinoma (80 papers, 2012 to 2025). "In addition, the positive correlations between ZC3H12C expression and highly connected CD8+ T genes were also visualized, including CD8A, CD8B, GZMA, GZMB, and PRF1 in colon adenocarcinoma and rectum adenocarcinoma." (PMID 38267865, 2024). "The Cancer Genome Atlas (TCGA)-colon adenocarcinoma (COAD) dataset was also analyzed to identify cytotoxic T lymphocyte (CTL) scores using a set of 5 previously reported genes (CD8A, CD8B, GZMA, GZMB, and PRF1) as a surrogate of tumor infiltrating CD8+ T cells." (PMID 38992029, 2024).
inflammatory bowel disease (79 papers, 2008 to 2026). A spectrum of small and large bowel inflammatory diseases of unknown etiology. "CEACAM5 expressed on intestinal epithelial cells (IECs) can bind with CD8α on CD8+ suppressor T cells, leading to the inhibition of CD8+ suppressor T cell activation and the increasing proliferation of CD4+ T cells in inflammatory bowel disease (IBD) patients." (PMID 38686388, 2024). "CD8α+ γδ T cell expansions have been described in transplant recipients receiving grafts from CMV-infected donors, CMV-infected fetuses, inflammatory bowel disease, in the context of aging (senescence) and CMV infection." (PMID 34696417, 2021).
neuroblastoma (77 papers, 2003 to 2025). Neuroblastoma (NB) is the most common solid, extracranial childhood tumor. "With the exception of ID2, all the other immune genes (CD8a, IL2, IL7R, IL6, ID3, and CXCR3) were also highly expressed in low-risk neuroblastoma patients further confirming the significance of these immune genes in neuroblastoma cases with favorable outcomes." (PMID 36068918, 2023). "Accordingly, the CD8α hinge and transmembrane domain may be an excellent choice to generate neuroblastoma-targeted CARs." (PMID 33322408, 2020). "Results from the present ex vivo study indicate that induction of neuroblastoma cell death by doxorubicin may enhance survival of tumor-bearing mice in vivo and promote proliferation of CD8α+ lymphocytes and IFN-γ production in vitro." (PMID 24520271, 2014).
fibrosis (73 papers, 2010 to 2025). the formation of excess fibrous connective tissue in an organ or tissue in a reparative or reactive process. "While TMNP show compelling efficacy in acute inflammation, key questions require resolution: First, whether CD4+CD8a+ T cell expansion predispose to post-VILI fibrosis merits investigation using lineage-tracing models." (PMID 40709179, 2025).
Cirrhosis (72 papers, 2008 to 2025). A chronic disorder of the liver in which liver tissue becomes scarred and is partially replaced by regenerative nodules and fibrotic tissue resulting in loss of liver function. "Therefore, we suggest that CD8A and CD247 may promote the progression of cirrhosis to HCC by mediating the chronic inflammatory response." (PMID 37461343, 2023).
depression (70 papers, 2014 to 2026). "CD5 and CD8A are expressed on T cells which have been implicated in the pathogenesis of depression." (PMID 39799156, 2025).
respiratory infections (68 papers, 2007 to 2025). "CD11c+CD8α+ cells exhibit mature dendritic cells phenotype and infiltrate cervical lymph nodes and lungs during early respiratory infection with Bordetella pertussis." (PMID 30001716, 2018).
kidney transplant (65 papers, 2012 to 2026). A surgical procedure in which one or both kidneys from a donor are implanted into a recipient. "In this study, CCR5, CD86, CD8A, ITGAM, and PTPRC were up-regulated and had the positive correlation with allograft rejection in kidney transplant patients." (PMID 36330810, 2022). "Five diagnostic genes were further identified, including CCR5, CD86, CD8A, ITGAM, and PTPRC, which were positively correlated with allograft rejection after the kidney transplant." (PMID 36330810, 2022).
toxoplasmosis (60 papers, 2009 to 2025). A parasitic disease contracted by the ingestion or fetal transmission of toxoplasma gondii. "Our current studies reveal that despite this return of CD8α DCs, CD4 T cells remain the dominant subset contributing to IFN-γ levels needed to control toxoplasmosis." (PMID 32669460, 2020).
Crohn disease (57 papers, 2012 to 2026). A gastrointestinal disorder characterized by chronic inflammation involving all layers of the intestinal wall, noncaseating granulomas affecting the intestinal wall and regional lymph nodes, and transmural fibrosis. "Further, in patients with ulcerative colitis and Crohn’s disease, the percentage of CD4+CD8α+ T cells is reduced in the intestinal mucosa, whereas the percentages in peripheral blood are increased." (PMID 23844100, 2013). "The percentage of CD4+CD8A+ T cells among the total CD4+ T cells in the inflamed intestine of the patients with Crohn’s disease was significantly reduced compared with that in the noninflamed intestine of the patients." (PMID 36353619, 2022).
myocardial infarction (55 papers, 2015 to 2026). Gross necrosis of the myocardium, as a result of interruption of the blood supply to the area, as in coronary thrombosis. "Plasma and tissue inflammation are exacerbated by higher levels of CCL11 and other cytokines in the CD8a+tm1mak mice (deficient in functional CD8 T-cells), leading to poor scar formation and the following cardiac rupture after myocardial infarction." (PMID 38906863, 2024). "Following co-localization analysis for myocardial infarction (MI), we focused on four potentially relevant genes: DPEP1, CD8A, CD30 Ligand, and HDHD2." (PMID 39715222, 2024).
prostate tumor (55 papers, 2010 to 2026). "Treatment of Hi-Myc mice with SFN for 16 weeks resulted in about 1.33-fold increase in the number of prostate tumor-infiltrating CD8α + T cells (p = 0.02 by Student's t-test)." (PMID 41802185, 2026).
diffuse large B-cell lymphoma (53 papers, 2014 to 2026). "To gain an insight into the role of immune checkpoints in canine diffuse large B-cell lymphoma (cDLBCL), we investigated PD-L1, PD-1 and CD8A expression by RNAscope." (PMID 34209830, 2021).
eosinophilia (48 papers, 2005 to 2025). "Compared to the OVA sensitized and OVA challenged (OVA/OVA) CD8α−/− mice, the recipients of the iTreg cells showed a significant increase in AHR, airway neutrophilia and eosinophilia and a visible increase in submucosal inflammatory cell infiltration." (PMID 37598239, 2023).
lupus nephritis (48 papers, 2013 to 2025). Glomerulonephritis in the context of systemic lupus erythematosus. "Induction of renal cleaved caspase-3 expression was strongly reduced in pristane-treated Cd8a-/- mice in comparison to diseased WT mice, further demonstrating the importance of CD8+ T cells for induction of apoptotic cell death in lupus nephritis." (PMID 35563816, 2022). "Interestingly, lack of CD8+ T cells in Cd8a-/- mice resulted in a reduced number of TUNEL+ tubular cells in lupus nephritis." (PMID 35563816, 2022).
endometriosis (45 papers, 2015 to 2025). The growth of functional endometrial tissue in anatomic sites outside the uterine body. "Focusing on the eutopic endometrial tissue in the secretory phase, single-cell RNA sequencing analysis did not reveal any difference in the expression of the CD8A gene between endometriosis and controls." (PMID 37497226, 2023).
ischemic stroke (45 papers, 2014 to 2026). A stroke disorder caused by obstruction of blood flow to the brain, due to thrombotic (local blood clot formation) or embolic (due to a blood clot or other material traveling from another site) event. "However, CD3+CD8a+ T cells and γδ T cells contribute to the secretion of perforin during the delayed phase of ischemic stroke." (PMID 34262436, 2021). "In addition, previous works suggested that CD3+CD4+ T cells, CD3+CD8a+ T cells, DNT cells, and γδ T cells exhibit diverse functions in ischemic stroke by regulating immunological and inflammatory homeostasis." (PMID 34262436, 2021).
nonalcoholic steatohepatitis (42 papers, 2009 to 2025). "Hepal-6-Luc cells expressing control (sgNC) or METTL3 knockout (sgMETL3) were implanted into the nonalcoholic steatohepatitis (NASH) livers of C57BL/6 mice, followed by treatment with anti-CD8α or immunoglobulin (Ig) G control." (PMID 37586322, 2023).
leprosy (38 papers, 2007 to 2025). Leprosy is a chronic infectious disease affecting primarily the skin and peripheral nervous system. "A cross-sectional study has demonstrated that five genes are associated with the outcome of T1R in leprosy patients: CCL2, CD8A, IL2, IL15, and MARCO." (PMID 34571865, 2021).
uveal melanoma (38 papers, 2011 to 2025). A melanoma derived from melanocytes of the uveal tract. "In contrast, low CD8A expression played a positive role in uveal melanoma (UVM) and brain low-grade glioma (LGG)." (PMID 36035168, 2022). "In particular, we found an antagonistic interaction between CD8A methylation levels and CTL levels in uveal melanoma and KIRP cohorts, corroborating its role in decreasing the beneficial association between CTL and survival outcome." (PMID 36035168, 2022).
primary immunodeficiency (36 papers, 2012 to 2026). "The circle plot representation of KEGG results highlighted specific enrichments: CD3E and CD8A were significantly enriched in primary immunodeficiency, while GZMB and PRF1 were notably enriched in allograft rejection." (PMID 39974584, 2025). "GSEA analysis adds more insight into the 23 ERBB2-related DEGs and primary immunodeficiency signaling pathway, showing that ERBB2-related DEGs associated with primary immunodeficiency were mainly down-regulated ERBB2-related DEGs, such as CD79A, CD19, CD3D, CD3E, CD8A, and CD4." (PMID 36437939, 2022). "The analysis of the altered pathways related to these genes showed the only significant KEGG pathway identified was “primary immunodeficiency pathway” (q-value <0.05), with three SDE genes upregulated (CD8A, CD8B, and TNFRSF13C) in HIV/HCV-f." (PMID 34497613, 2021).
cervical squamous cell carcinoma (34 papers, 2002 to 2026). A squamous cell carcinoma arising from the cervical epithelium. "Through further analysis of cervical squamous cell carcinoma data in the TCGA database (n = 253), the expression of PD-L1 (CD274) was positively correlated with CD8A." (PMID 39489086, 2024).
Salmonella Infections (31 papers, 2006 to 2025). Infections with bacteria of the genus SALMONELLA. "Our data revealed a significant expansion in the absolute number of CD8α+CD4+TCR1- cells in peripheral blood following Salmonella infection." (PMID 40438105, 2025). "Taken together, Ascaris infection trends toward a modified type 2 response characterized by Th2 cells as seen in the blood and lung and dominant CD4 as well as CD8α Treg cells, while pigs responded to Salmonella infection with relatively prominent local Th1 and Th17 cell responses." (PMID 39140728, 2024). "Further, we explored the compensatory potential of the TCR1- cell subset in the absence of γδ T cells by analyzing the occurrence of CD8α+ NK-like cells in PBMCs, spleen, and cecum of chickens following Salmonella infection." (PMID 40438105, 2025).
leukopenia (30 papers, 2012 to 2026). "Intriguingly, both WT IL-1β and CD8α ALN-1 elicit leukopenia, which we found is primarily due to a reduction in circulating lymphocytes as the level of neutrophils remains unaltered." (PMID 32714571, 2020). "We looked further into this leukopenia and observed that, based on Hemavet 950FS measurements, this decrease in circulating lymphocytes is apparent 6 h after treatment and is thereafter further maintained when CD8α ALN-1 is repeatedly administered." (PMID 32714571, 2020).
skin cancer (27 papers, 2012 to 2025). "Our results show that a marked correlation between the CD103+DC signature (IRF8, FMS‐like tyrosine kinase 3 ligand, CLEC9A, CLNK, XCR1, BATF3, and ZBTB46) and chemokines C‐X‐C motif chemokine ligand 9, CXCL10, and CD8A in a mouse model with DMBA/TPA‐induced skin cancer." (PMID 36891351, 2023).
Anxiety (25 papers, 2019 to 2025). Intense feelings of nervousness, tension, or panic often arise in response to interpersonal stresses. "To further demonstrate the function of CD8+ T cells induced by HBV to regulate brain function, i.e. to reduce neurogenesis and anxiety-like behaviour, we tested the neuronal proliferation in the hippocampus and anxiety-like behaviour in HBV mice after anti-CD8α neutralizing antibodies treatment." (PMID 39386089, 2024).
relapsing-remitting MS (25 papers, 2009 to 2025). "In patients with untreated chronic HIV infections, higher frequencies of CD8α+ NK cells were correlated with slower disease progression, while a CD8+ NK transcriptomic signature was associated with reduced relapse risk in patients with relapsing-remitting multiple sclerosis." (PMID 38805302, 2024).
bacteremia (23 papers, 2010 to 2024). "Our data revealed that langerin+ CD8α+ DCs play a pivotal role in initiating CD8+ T cell responses and IL-12 production in response to bacteremia and may influence the early control of systemic bacterial infections." (PMID 29867941, 2018).
skin infection (23 papers, 2010 to 2025). An inflammatory process affecting the skin, caused by bacteria, viruses, parasites, or fungi. "During skin infection with herpes simplex virus (HSV)-1, LN-resident CD8α+ DCs and skin-derived CD103+ DCs can activate naïve CD8+ T-cells, presumably through the cross-presentation pathway involving the acquisition of noninfectious antigen." (PMID 25121482, 2014).
chronic myeloid leukemia (21 papers, 2010 to 2025). "Studies on mice with a knockout of the Irf8 gene revealed that the absence of CD8α+ dendritic cells and macrophage functions, along with the production of abnormal granulocytes, was linked to the development of an atypical form of chronic myelogenous leukemia (CML)." (PMID 38472940, 2024).
juvenile idiopathic arthritis (21 papers, 2006 to 2025). Juvenile idiopathic arthritis (JIA) is the term used to describe a group of inflammatory articular disorders of unknown cause that begin before the age of 16 and last over 6 weeks. "Finally, T cell clones expressing CD4 and CD8α have also been generated from a patient with lepromatous leprosy and from joint fluid of patients with juvenile rheumatoid arthritis." (PMID 23844100, 2013).
Infertility (20 papers, 2009 to 2025). "No or only negligible expression of hematopoietic and endothelial cell markers (CD14, CD8a, CD15, CD31, CD34, CD45, CD117 and CD133) was detected in MenSCs from healthy volunteers and patients with unexplained infertility." (PMID 34202508, 2021).